UBLCP1 (ubiquitin like domain containing CTD phosphatase 1)
Description:
Dephosphorylates 26S nuclear proteasomes, thereby decreasing their proteolytic activity. Recruited to the 19S regulatory particle of the 26S proteasome through its interaction with 19S component PSMD2/RPN1. Once recruited, dephosphorylates 19S component PSMC2/RPT1 which impairs PSMC2 ATPase activity and disrupts 26S proteasome assembly. Has also been reported to stimulate the proteolytic activity of the 26S proteasome.
Synonyms: MGC10067; CPUB1
Tractability: Small molecule: a high-quality ligand is known. PROTAC: ubiquitination databases record sites on it; its protein half-life has been measured; a small molecule that binds it is known.
Target class: Protein Phosphatase; Phosphatase; Serine/threonine protein phosphatase; Enzyme
Gene: Protein-coding gene on chromosome 5 (159,263,285 to 159,286,037, forward strand). Ensembl gene ENSG00000164332.
Subcellular location: Nucleus
Subcellular location (Human Protein Atlas): Nucleoli; Nucleoli rim; Nucleoplasm
Gene Ontology:
Molecular function: proteasome regulatory particle binding; protein binding; protein serine/threonine phosphatase activity; phosphoprotein phosphatase activity
Biological process: negative regulation of ATP-dependent activity; regulation of proteasome assembly
Cellular component: nucleolus; nucleoplasm; nucleus
Genetic constraint (gnomAD): Loss-of-function variants: 18 observed, 26.74 expected, observed/expected ratio (o/e) 0.67, 90% interval 0.46 to 1. The upper end of that interval is the gene's LOEUF score, 1, which puts it in group 4 of 6, group 1 being the genes least tolerant of losing a copy. Missense variants: 245 observed, 322.38 expected, observed/expected ratio (o/e) 0.76, 90% interval 0.68 to 0.85. Synonymous variants: 103 observed, 106.08 expected, observed/expected ratio (o/e) 0.97, 90% interval 0.83 to 1.14.
Homologues: Orthologues: chimpanzee UBLCP1 (100% identical), dog UBLCP1 (100% identical), pig UBLCP1 (100% identical), rabbit UBLCP1 (99% identical), guinea pig UBLCP1 (99% identical), macaque UBLCP1 (98% identical), mouse Ublcp1 (98% identical), rat Ublcp1 (98% identical), tropical clawed frog ublcp1 (86% identical), zebrafish ublcp1 (84% identical), zebrafish UBLCP1 (74% identical), Drosophila melanogaster Ublcp1 (62% identical).
Diseases named in the same sentence as UBLCP1 in open-access papers:
UBLCP1 is named in the same sentence as 11 diseases in open-access papers, as found by Europe PMC text mining. Sharing a sentence is not in itself a finding about the gene and the disease. The quoted sentences say what the papers report.
ovarian carcinoma (1 paper, 2017). A malignant neoplasm originating from the surface ovarian epithelium. "On the contrary, UBLCP1 does not impair the viability of the A2780 ovarian cancer cell line, harbouring an intact Rpt1 copy number." (PMID 28539385, 2017). "We find that overexpression of UBLCP1, but not DDAA, significantly impairs the viability of the SKOV3 ovarian cancer cell line, harbouring partial Rpt1 copy number loss (data not shown)." (PMID 28539385, 2017).
parasite infection (1 paper, 2025). "Stimulated by the results of UBLCP1 and its crucial roles in the lytic cycle and mitochondrial integrity of T. gondii tachyzoites, we tested their essentialities in parasite infection and pathogenesis in vitro." (PMID 40156024, 2025).
toxoplasmosis (1 paper, 2025). A parasitic disease contracted by the ingestion or fetal transmission of toxoplasma gondii. "UBLCP1 is a candidate target for a vaccine or a drug for toxoplasmosis in animals." (PMID 40156024, 2025).
tuberculosis (1 paper, 2017). A chronic, recurrent infection caused by the bacterium Mycobacterium tuberculosis. "Interestingly, susceptibility to tuberculosis in an African cohort has been associated with a separate SNP cluster 3’ of the IL12B locus and of the neighbouring UBLCP1 gene." (PMID 28263993, 2017).
tumor (2 papers, 2009 to 2017). "Likewise, Ublcp1 is upregulated in fast growing or tumor tissues perhaps through its activity as a regulator of the phosphorylation state of RNA Polymerase II." (PMID 19426526, 2009). "We speculate that the anti-tumour effect of UBLCP1 in SKOV3 cells is based on Rpt1 inhibition." (PMID 28539385, 2017).
heart diseases (1 paper, 2017). "Conversely, proteasome activation can be beneficial in treating neurodegenerative and heart diseases, which can be achieved by kinase activators (as in the case of PKA and PKG) or phosphatase inhibitors (as in the case of UBLCP1)." (PMID 28258412, 2017).
infection (1 paper, 2025). The state of being infected such as from the introduction of a foreign agent such as serum, vaccine, antigenic substance or organism. "Mice also survived from the infection with 1,000, 10,000, and even 100,000 ΔUBLCP1 tachyzoites, suggesting attenuated virulence of the UBLCP1 deletion mutant." (PMID 40156024, 2025). "Hence, in this study, we investigate the roles of UBLCP1 systematically in the growth, survival, and pathogenicity of tachyzoites (the acute infection stage) of T. gondii, to explore the essentiality of this phosphatase in the mitochondrial biology of this important parasite." (PMID 40156024, 2025).
UBLCP1 also shares sentences with these, for which no sentence is quoted: autism (1 paper); diabetes (1); Peri-Implantitis (1); prostate carcinoma (1).